CCND3 (cyclin D3)
Description:
Regulatory component of the cyclin D3-CDK4 (DC) complex that phosphorylates and inhibits members of the retinoblastoma (RB) protein family including RB1 and regulates the cell-cycle during G(1)/S transition. Phosphorylation of RB1 allows dissociation of the transcription factor E2F from the RB/E2F complex and the subsequent transcription of E2F target genes which are responsible for the progression through the G(1) phase. Hypophosphorylates RB1 in early G(1) phase. Cyclin D-CDK4 complexes are major integrators of various mitogenenic and antimitogenic signals. Component of the ternary complex, cyclin D3/CDK4/CDKN1B, required for nuclear translocation and activity of the cyclin D-CDK4 complex. Shows transcriptional coactivator activity with ATF5 independently of CDK4.
Tractability: Small molecule: a structure with a bound ligand is known; a high-quality ligand is known; it belongs to a druggable protein family. PROTAC: UniProt records ubiquitination sites on it; ubiquitination databases record sites on it; a small molecule that binds it is known.
Target class: Other cytosolic protein
Gene: Protein-coding gene on chromosome 6 (41,934,934 to 42,050,357, reverse strand). Ensembl gene ENSG00000112576.
Subcellular location: Nucleus; Cytoplasm
Subcellular location (Human Protein Atlas): Nucleoplasm; Cytosol
Pathways (Reactome):
Cell Cycle: Cyclin D associated events in G1; Drug-mediated inhibition of CDK4/CDK6 activity
Developmental Biology: Transcriptional regulation of white adipocyte differentiation
Disease: Defective binding of RB1 mutants to E2F1,(E2F2, E2F3)
Gene expression (Transcription): Regulation of RUNX1 Expression and Activity
Signal Transduction: MAPK6/MAPK4 signaling
Gene Ontology:
Molecular function: cyclin-dependent protein serine/threonine kinase activator activity; protein binding; protein kinase binding; protein serine/threonine kinase activator activity; cyclin-dependent protein serine/threonine kinase regulator activity; cyclin-dependent protein serine/threonine kinase activity
Biological process: G1/S transition of mitotic cell cycle; positive regulation of G1/S transition of mitotic cell cycle
Cellular component: cyclin D3-CDK4 complex; cyclin D3-CDK6 complex; cyclin-dependent protein kinase holoenzyme complex; cytoplasm; cytosol; nucleoplasm; nucleus; microtubule organizing center
Genetic constraint (gnomAD): Loss-of-function variants: 9 observed, 28.68 expected, observed/expected ratio (o/e) 0.31, 90% interval 0.19 to 0.55. The upper end of that interval is the gene's LOEUF score, 0.55, which puts it in group 2 of 6, group 1 being the genes least tolerant of losing a copy. Missense variants: 315 observed, 391.51 expected, observed/expected ratio (o/e) 0.8, 90% interval 0.73 to 0.88. Synonymous variants: 164 observed, 163.18 expected, observed/expected ratio (o/e) 1, 90% interval 0.88 to 1.14.
Homologues: Orthologues: chimpanzee CCND3 (99% identical), dog CCND3 (98% identical), pig CCND3 (98% identical), mouse Ccnd3 (95% identical), rat Ccnd3 (95% identical), rabbit CCND3 (77% identical), macaque CCND3 (70% identical), guinea pig CCND3 (67% identical), tropical clawed frog ccndx (51% identical), Drosophila melanogaster CycD (40% identical), zebrafish ccndx (36% identical), Caenorhabditis elegans cyd-1 (25% identical), and 10 more. Paralogues in human: CCND2 (61% identical), CCND1 (52% identical), CCNA1 (28% identical), CCNA2 (27% identical), CCNB2 (25% identical), CCNB1 (23% identical), CCNO (22% identical), CCNE2 (22% identical), CCNE1 (22% identical), CCNF (21% identical), CCNI (21% identical), CCNJ (21% identical), and 6 more.
Diseases named in the same sentence as CCND3 in open-access papers:
CCND3 is named in the same sentence as 123 diseases in open-access papers, as found by Europe PMC text mining. Sharing a sentence is not in itself a finding about the gene and the disease. The quoted sentences say what the papers report.
breast carcinoma (53 papers, 2008 to 2025). "It has been reported that cyclin D1 and D3 are critical for the growth of breast cancer cells in vitro and in vivo, with loss of cyclin D3 resulting in compensatory upregulation of cyclin D1." (PMID 35406445, 2022). "CCND3 variants have also been described in breast cancer, but their functional relevance remains to be determined." (PMID 34281234, 2021). "Rapamycin causes a G1 arrest in HER-2-overexpressing breast cancer cells that is associated with a differential destabilization and subsequent down-regulation of Cyclin D3 protein level." (PMID 26412984, 2015). "It is possible that CCND3 rs2479717, or another variant it tags, is associated with prognosis after a diagnosis of breast cancer." (PMID 18507837, 2008). "One SNP, CCND3 rs2479717, showed a significant association with survival after a diagnosis of breast cancer (unadjusted P value = 0.0001)." (PMID 18507837, 2008). "Our study has found evidence that tagSNP CCND3 rs2479717, which is found in a genomic region that includes CCND3 and six other genes, is associated with survival after a diagnosis of breast cancer." (PMID 18507837, 2008). "Furthermore, expression of Cyclin D3 was significantly associated with BC prognosis and was shown to be an independent prognostic marker in breast cancer (p = 0.028)." (PMID 26412984, 2015). "An additional line of support for a patho-physiologically relevant role of In1-ghrelin in breast cancer arises from the positive association in breast cancer samples between In1-ghrelin expression and Ki67 and cyclin-D3, two markers linked to proliferation and ductal breast tumor grade." (PMID 21829727, 2011). "The overexpression of KNSTRN enhanced the expression of key cell cycle regulators, including CDK4, CDK6, and cyclin D3, thereby accelerating the G1/S phase transition and leading to aberrant proliferation of breast cancer cells." (PMID 38198023, 2024). "It has been reported that aberrant cyclin D3 expression was found in various cancers, including leukemia, hepatocellular carcinoma, gliomas, bladder carcinoma, prostate cancer, osteosarcoma and breast cancer." (PMID 35548329, 2022). "We showed that the post‐translational downregulation of CDC6, CDK2, Cyclin D1 and Cyclin D3 is part of the mechanism to reduce breast cancer cell viability." (PMID 33124043, 2021). "Cyclin D3 has also been reported to be overexpressed in breast cancer samples, but there are limited research data on its relationship to disease outcomes." (PMID 33920506, 2021). "Another study identified that 64 breast cancer cases out of 82 had cyclin D1 gene amplification, and 36 out of 86 cases had cyclin D3 gene amplification." (PMID 33920506, 2021). "In contrast, CYCLIN D3 protein levels were increased in all three types of breast cancer cells compared to normal HMECs." (PMID 33462997, 2021). "For instance, only low doses of garcinol (1 uM) from the edible fruit Garciniaindica had inhibited nicotine induced breast cancer cell proliferation through the downregulation of α9-nAChR and cyclin D3 expression." (PMID 31963558, 2020). "Tissue sections including both invasive tumor and adjacent benign components from 21 breast cancer patients with high grade tumors were immunostained for K19, cyclin D1 and cyclin D3 and semiquantitatively scored for their immunoreactivity." (PMID 31601969, 2019). "But just on account of the restricted amounts of selected researches, we only evaluated the prognostic value of cyclin D3 in mammary tumor and lymphoma." (PMID 31198407, 2019). "It has been demonstrated that the beneficial anticancer effect of rapamycin is mainly based on the arresting cells in G1 phase due to destabilization and subsequent down-regulation of cyclin D3 protein in HER2-overexpressing breast cancer cells." (PMID 29963272, 2018). "Taken together, PAK5 can augment the expression of Cyclin D1 and Cyclin D3 and inhibit the expression of p21 and p27, accelerating cell-cycle progression in breast cancer cells." (PMID 29041983, 2017).
breast carcinoma (continued). "It showed that the mRNA level of Cyclin D3 was extremely high in the breast cancer tissues compared with the adjacent tissues (p < 0.05)." (PMID 26412984, 2015). "We also detected the proteins which interacted with Cyclin D3 to further elucidate the mechanism in Cyclin D3 mediated pathway in breast cancer." (PMID 26412984, 2015). "Further investigation revealed that Cyclin D3 prompted the migration and invasion of breast cancer cells." (PMID 26412984, 2015). "Our studies revealed that Cyclin D3 was upregulated in breast cancer and represented a novel predictor of BC prognosis." (PMID 26412984, 2015). "Breast cancer tissue array was employed to examine Cyclin D3 expression in breast cancer patients and its relationship with the patients’ prognosis." (PMID 26412984, 2015). "Previous studies showed that Cyclin D1 and D3 are overexpressed in human breast cancer cell lines and primary invasive breast cancers and Cyclin D3 frequently exceeded the expression of Cyclin D1 in ErbB2-positive cases." (PMID 26412984, 2015). "The results showed that DFS was significantly worse in breast cancer patients with high Cyclin D3 expression (p = 0.01), although overall survival (OS) showed no statistical significance (p = 0.088)." (PMID 26412984, 2015). "Consistent with our clinical cohort result, we also noted significantly worse DFS of breast cancer patients in the Cyclin D3 high expression group." (PMID 26412984, 2015). "Through detecting Cyclin D3 expression in 243 breast cancer patients’ tissue array, we found Cyclin D3 expression was correlated with ER status (p = 0.000), PR status (p = 0.001), HER2 status (p = 0.002) and tumor differentiation (p = 0.045)." (PMID 26412984, 2015). "When we detected Cyclin D3 expression in tissue array, we found that expression of Cyclin D3 was higher in breast cancer tissues than in normal adjacent breast tissues." (PMID 26412984, 2015). "As expected, the expression levels of two key tumoral markers of cell proliferation, Ki67 and cyclin-D3, were highly up-regulated in breast cancer samples as compared to their matched controls (p<0.01)." (PMID 21829727, 2011). "A previous study in breast cancer cells suggested a role for PEA3 in proliferation control as it was shown that PEA3 regulates Cyclin D3 expression, a key regulator of the cell cycle and affects cell cycle progression." (PMID 21143918, 2010). "Breast cancer-specific mortality was available from death certificates, and the results were consistent for the breast cancer-specific analysis, with an identical HR for CCND3 rs2479717." (PMID 18507837, 2008). "Additionally, cyclin D3 has been reported to be used as a predictive marker in breast cancer, and its reduction decreases malignant cell migration and invasion." (PMID 35216267, 2022). "CDK14 has been shown to interact with other cyclins as well, such as cyclin B to activate the Wnt pathway in breast cancer, cyclin D3 to regulate cell cycle progression and proliferation in mammalian cells, and the CDK7/cyclin H complex to regulate proliferation and migration in esophageal cancer." (PMID 34571979, 2021). "Furthermore, experimental evidence has also shown elevated cyclin D1 protein levels and deposition of cyclin D3 in breast cancer samples." (PMID 33920506, 2021). "Zhang et al43 reported the lack of CCND1 was associated with a compensatory upregulation of CCND3 and the inhibition of both CCND1 and CCND3 could be a suitable strategy for breast cancer prevention and therapy." (PMID 30950241, 2019). "CCND3 play an oncogenic role in breast cancer, which is consistent with the viewpoints above." (PMID 30950241, 2019). "In addition, CCND3 was correlated to reduced OS in breast cancer patients (HR = 1.64, 95% CI: 1.07‐2.52) and shorter DFS/PFS/RFS in bladder cancer patients (HR = 4.60, 95% CI: 1.89‐12.57)." (PMID 30950241, 2019).
breast carcinoma (continued). "Moreover, nicotine can induce human breast cancer cell proliferation through downregulation of the nicotinic receptor and cyclin D3." (PMID 28878681, 2017). "Expression of Cyclin D3 was also detected in the breast cancer cell lines by qPCR and western blot." (PMID 26412984, 2015). "In this study, we provided the evidence that Cyclin D3 predicted disease-free survival in breast cancer and could serve as an independent prognostic biomarker in breast cancer." (PMID 26412984, 2015). "We demonstrated here that Cyclin D3 was up-regulated in breast cancer." (PMID 26412984, 2015). "E1AF promotes breast cancer cell cycle progression via upregulation of Cyclin D3 transcription." (PMID 26412984, 2015). "Therefore, the downregulation of E2F1, CDK4, cyclin D1 and cyclin D3 and upregulation of p27 and p21 in breast cancer cells likely contributed to the G1 cell cycle arrest induced by 5a." (PMID 25766325, 2015). "Analysis of the primary breast cancer cell lines, which were isolated from the human tumor samples, further confirmed that 5a significantly inhibited Akt Ser473 and Bad Ser136 phosphorylation and reduced cyclin D3 expression." (PMID 25766325, 2015). "Then we wondered how Cyclin D3 regulated the progression of breast cancer." (PMID 26412984, 2015). "Cyclin D3 was higher in breast cancer cells than in the normal breast cell line MCF10A." (PMID 26412984, 2015). "DFS was significantly worse in breast cancer patients with high Cyclin D3 expression (p = 0.01)." (PMID 26412984, 2015). "Literature reports revealed that miR-195 could inhibit cell invasion by inhibiting CCND1 and CCND3 in breast cancer cells and gliobalstoma cells." (PMID 22723898, 2012). "While CDK6/cyclin D3 is linked to the hematopoietic system and is crucial for healthy thymus development and the maturation of bone marrow hematopoietic stem cells, CDK4/cyclin D1 is related to cell proliferation and is essential for supporting the progression of breast cancer." (PMID 37759823, 2023). "Notably, among those genetic alteration events whose loss enhances CDK4/6i sensitivity, CDK6, CCND3, CCNE1 and E2F3 were frequently amplified in the genomes of breast cancer patients, whereas among the genes whose loss promotes resistance, RB1, REXO2, PPP2R2A and STT3A were mainly depleted." (PMID 34508104, 2021). "In addition, CCND3 overexpression was an adverse predictor of OS in breast cancer." (PMID 30950241, 2019). "In addition, CCND3 was an adverse prognostic factor in breast cancer and bladder cancer." (PMID 30950241, 2019). "All these studies showed that Cyclin D3 might play an important role in breast cancer." (PMID 26412984, 2015). "Nuclear actin was reported to be involved in the gene transcription regulation, so we speculated that Cyclin D3 promoted the progression and invasion of breast cancer by interacting with actin to regulate some metastasis related genes or oncogene transcription." (PMID 26412984, 2015). "Interestingly, the levels of expression of In1-ghrelin variant and GOAT levels showed a trend to or were positively correlated with the expression of Ki67 (p = 0.069 and p = 0.109, respectively) and cyclin-D3 (p = 0.009 and p = 0.059, respectively) in breast cancer samples." (PMID 21829727, 2011). "Our study further revealed that miR‐195‐5p transfection led to the downregulation of CCND3, CDK4, and PLK1 in all studied breast cancer cell lines." (PMID 40548926, 2025). "Among the genes regulated by Bcl-2 in both melanoma and breast carcinoma models we identified CTGF, CCND3, TEAD2, FST, MYC and TP73." (PMID 38755629, 2024). "Our previous study demonstrated that IGFBP-3 induced G1 cell cycle arrest by inhibiting cyclin D1, cyclin D3, cyclin E, cyclin A, CDK2, CDK4, total and phospho-pRb, and increasing p21 and p16 in MCF-7 breast cancer cells." (PMID 37253773, 2023).
breast carcinoma (continued). "Next, RNA and protein expression of CCND3, DUSP10 and RAP1GAP was evaluated on breast cancer cell lines with known gene expression data to assess the correlation between gene and protein expression of these genes." (PMID 34440000, 2021). "In breast cancer, ETV4 down-regulates the expression of the cyclin D2 gene and up-regulates the expression of the cyclin D3 gene to promote cell proliferation." (PMID 34736492, 2021). "In pancreatic cancer and breast cancer, ETV4 directly upregulates the transcription of cyclin proteins, such as cyclin D1 and cyclin D3 to promote cell proliferation." (PMID 32018225, 2020). "Analysis of the primary breast cancer cell lines with HER2 overexpression further confirmed that 5a significantly inhibited Akt Ser473 and Bad Ser136 phosphorylation and reduced cyclin D3 expression." (PMID 25766325, 2015). "miR-503-5p was already emphasized in our previous work: this microRNA is highly expressed in endothelial cells and, can be secreted in exosomes and transferred into breast cancer cell lines to inhibit tumor growth by targeting CCND2 and CCND3." (PMID 26490435, 2015). "However, the role of Cyclin D3 in breast cancer (BC) remains unknown." (PMID 26412984, 2015). "In breast cancer, KRT19 is found to mediate cell cycle arrest, a typical characteristic of senescence by physically interacting with GSK3β and thus restrain GSK3β-dependent degradation of cyclin D3." (PMID 41345704, 2025). "When analyzing breast cancer tumors, including IDCs and ILCs, we observed new mutations in CDKN2A, RB1, CCND2, and CCND3 in the brain metastases of four IDCs, but not in their primary tumor counterparts." (PMID 36507516, 2022). "Indeed, ubiquitin-mediated degradation of CCND3 by FBXL2 has been demonstrated in lung cancer, while in breast cancer cells, the RNA-binding protein IMP-3 can regulate CCND3 protein expression by directly binding to its mRNAs." (PMID 34440000, 2021). "Mechanistically, we showed that both knockdown of PTTG1 expression and simvastatin treatment potently attenuated breast cancer cell invasion, presumably through inhibition of the expression of PTTG1 downstream target genes, such as MMP-2, MMP9, c-myc, FGF-2, and cyclin D3." (PMID 33250768, 2020). "High expression of CSNK2B (p = 0.0041, HR = 1.37), GRPEL1 (p = 0.0200, HR = 1.29) and QARS (p = 0.0350, HR = 1.26) were corelated with worse prognosis in breast cancer patients, whereas CCND3, HDAC3, SH3BGRL3, SRM, and UBE2D4 were not correlated with OS." (PMID 31781497, 2019). "miR-195 was shown to inhibit cyclin D1 in HCC and breast cancer, CCND3 in glioblastoma, CDK4 in bladder cancer, CDK6 in HCC, E2F3 in HCC and glioblastoma, BCL-2 in breast and colorectal cancer, RAF1 in breast cancer, and GLUT3 in bladder cancer." (PMID 23335942, 2012). "Furthermore, RNAi-mediated knock-down of Pea3 in mouse mammary tumor cells leads to decreased expression of multiple PEA3 gene targets with established proneoplastic roles, including Cox-2, vimentin, Cyclin D3, HER2/neu and several MMP genes." (PMID 20107508, 2010). "Furthermore, a functional variant tagged by this SNP may not even alter the function of CCND3; the SNP lies in a large LD block with several genes that are reasonable candidates for breast cancer survival." (PMID 18507837, 2008).